SCD (stearoyl-CoA desaturase)
Description:
Stearoyl-CoA desaturase that utilizes O(2) and electrons from reduced cytochrome b5 to introduce the first double bond into saturated fatty acyl-CoA substrates. Catalyzes the insertion of a cis double bond at the delta-9 position into fatty acyl-CoA substrates including palmitoyl-CoA and stearoyl-CoA. Gives rise to a mixture of 16:1 and 18:1 unsaturated fatty acids. Plays an important role in lipid biosynthesis. Plays an important role in regulating the expression of genes that are involved in lipogenesis and in regulating mitochondrial fatty acid oxidation (By similarity). Plays an important role in body energy homeostasis (By similarity). Contributes to the biosynthesis of membrane phospholipids, cholesterol esters and triglycerides (By similarity).
Synonyms: hSCD1; FADS5; SCD1; SCDOS; MSTP008
Tractability: Small molecule: a structure with a bound ligand is known; a high-quality ligand is known; it belongs to a druggable protein family. Antibody: UniProt predicts a signal peptide or a membrane-spanning region. PROTAC: ubiquitination databases record sites on it; its protein half-life has been measured; a small molecule that binds it is known.
Target class: Enzyme
Chemical probes: CHEMBL1087014
Safety:
Unwanted effects reported when the protein is acted on. In parentheses: how it was acted on, where the effect was seen, and who reports it.
Increased, Liver Steatosis (activation; source: AOP-Wiki)
Accumulation, Liver lipid (activation; source: AOP-Wiki)
N/A, Liver Steatosis (activation; source: AOP-Wiki)
Gene: Protein-coding gene on chromosome 10 (100,346,508 to 100,364,837, forward strand). Ensembl gene ENSG00000099194.
Subcellular location: Endoplasmic reticulum membrane
Subcellular location (Human Protein Atlas): Endoplasmic reticulum
Pathways (Reactome):
Metabolism: Activation of gene expression by SREBF (SREBP); Fatty acyl-CoA biosynthesis
Gene expression (Transcription): MLL4 and MLL3 complexes regulate expression of PPARG target genes in adipogenesis and hepatic steatosis
Signal Transduction: NR1H2 & NR1H3 regulate gene expression linked to lipogenesis
Gene Ontology:
Molecular function: iron ion binding; oxidoreductase activity; palmitoyl-CoA 9-desaturase activity; protein binding; stearoyl-CoA 9-desaturase activity; oxidoreductase activity, acting on paired donors, with oxidation of a pair of donors resulting in the reduction of molecular oxygen to two molecules of water
Biological process: unsaturated fatty acid biosynthetic process; monounsaturated fatty acid biosynthetic process; positive regulation of cold-induced thermogenesis; fatty acid biosynthetic process
Cellular component: endoplasmic reticulum; endoplasmic reticulum membrane; membrane
Genetic constraint (gnomAD): Loss-of-function variants: 4 observed, 37.86 expected, observed/expected ratio (o/e) 0.11, 90% interval 0.051 to 0.24. The upper end of that interval is the gene's LOEUF score, 0.24, which puts it in group 1 of 6, group 1 being the genes least tolerant of losing a copy. Missense variants: 282 observed, 479.04 expected, observed/expected ratio (o/e) 0.59, 90% interval 0.53 to 0.65. Synonymous variants: 150 observed, 177.17 expected, observed/expected ratio (o/e) 0.85, 90% interval 0.74 to 0.97.
Homologues: Orthologues: chimpanzee SCD (99% identical), macaque SCD (94% identical), dog SCD (90% identical), pig SCD (87% identical), mouse Scd2 (83% identical), rat Scd2 (81% identical), mouse Scd4 (77% identical), tropical clawed frog scd (57% identical), zebrafish scd (57% identical), zebrafish scdb (55% identical), Caenorhabditis elegans fat-6 (44% identical), Caenorhabditis elegans fat-7 (44% identical), and 1 more. Paralogues in human: SCD5 (53% identical).
Diseases named in the same sentence as SCD in open-access papers:
SCD is named in the same sentence as 289 diseases in open-access papers, as found by Europe PMC text mining. Sharing a sentence is not in itself a finding about the gene and the disease. The quoted sentences say what the papers report.
Obesity (282 papers, 2005 to 2026). Accumulation of substantial excess body fat. "Genetic variation in the SCD coding gene, SCD1 have been reported to potentially influence individual FA metabolism and, hence, the risk for obesity." (PMID 40598589, 2025). "SCD is essential for normal cellular function and has been implicated in a number of inflammatory diseases, including obesity and insulin resistance." (PMID 38032369, 2024). "DHA was associated with increased DNAm in the SCD gene, which encodes the Stearoyl CoA Desaturase-1 enzyme that converts saturated fatty acids into monounsaturated fatty acids and plays a role in obesity and insulin resistance." (PMID 37858220, 2023). "Both FAS and SCD, as important factors in de novo lipogenesis, have been proven to be associated with the development of obesity." (PMID 38068770, 2023). "The gene for SCD-1 is suppressed by leptin, and the suppression of SCD-1 can lead to a considerable loss of weight in people affected by obesity." (PMID 36765351, 2023). "Studies have shown that SCD-deficient mice showed reduced adiposity and adipocyte inflammation, and SCD activity was positively associated with obesity and insulin resistance in humans." (PMID 37239856, 2023). "The deficient SCD-1 activity was reported to contribute to reducing body adiposity, increasing insulin sensitivity, and alleviating diet-induced obesity." (PMID 35406114, 2022). "Plasma SCD indices have previously been associated with obesity, and Scd1 expression is down-regulated by the intake of polyunsaturated fatty acids (PUFA) in mice." (PMID 30477080, 2018). "The enzyme responsible for MUFA OA biosynthesis is SCD, which is considered as a key enzyme in de novo lipogenesis, a process that is associated with obesity, synthesis of cholesterol and apoptosis." (PMID 27875996, 2016). "Stearoyl-CoA desaturase 1 (SCD1) is a lipogenic enzyme important for the regulation of membrane lipid homeostasis; dysregulation likely contributes to obesity associated metabolic disturbances." (PMID 27632198, 2016). "The regulation of SCD1 gene is of considerable physiological importance, as a high SCD activity has been implicated in a wide range of disorders including diabetes, atherosclerosis, cancer, and obesity." (PMID 27562731, 2016). "Up-regulation of the SCD gene in skeletal muscle has been associated with abnormal lipid partitioning and obesity in humans and lower levels of SCD with a leaner body type." (PMID 27506674, 2016). "Mice with SCD gene deficiency had increased insulin signalling/sensitivity and were resistant to diet-induced obesity, despite increased food intake." (PMID 25938677, 2015). "Obesity has been associated with a greater saturated fatty acid content of adipose tissue, and estimates of the activity of SCD within adipose tissue are increased in obesity and insulin resistance." (PMID 22721353, 2012). "Obesity and its metabolic complications are associated with increased expression/activity of stearoyl-CoA desaturase-1 (SCD1), a major regulator of lipid metabolism." (PMID 23209931, 2012). "Previously, a high SCD-16 and D6D index was associated with obesity and predicted the metabolic syndrome, associations that was confounded by obesity." (PMID 19712485, 2009). "Increased stearoyl-CoA desaturase activity is associated with obesity, which can explain the positive association between pBMI and MUFA (C16:1–n7, C18:1–n7, C18:1–n9), as well as the corresponding LysoPC (Lysopc16:1, LysoPC18:1) and the concurrent negative association of PC36:0." (PMID 40228714, 2025). "Upregulation of miR-199a-3p could reduce adipocyte differentiation by targeting SCD, which could alter the composition of fat in the body and reduce the risk of obesity." (PMID 39457531, 2024). "A recent study found that SCD-1-deficient mice are protected against obesity, MetS, CVD, and NAFLD." (PMID 39458502, 2024). "Decreased promoter methylation of the SCD gene has been previously linked to obesity." (PMID 37858220, 2023).
Obesity (continued). "Systemic SCD inhibition, despite its anti-obesity effect under HFD conditions, predisposes to atherosclerosis, but under certain conditions it may have an anti-atherosclerotic effect." (PMID 36982607, 2023). "Stearoyl-CoA desaturase (SCD), including delta-9–18 desaturase [octadecenoic acid/octadecanoic acid], converts saturated fatty acids (SFAs) into monounsaturated fatty acids (MUFAs), which are linked to obesity, insulin resistance, and hypertension." (PMID 35898714, 2022). "On the other hand, SCD could be detrimental because data from Scd1-knockout mice show that Scd1 deficiency protects the heart against obesity-induced cardiac damage of ob/ob mice." (PMID 34576047, 2021). "Moreover, mice that lack SCD-1 are protected against diet-induced obesity, while increased SCD-1 activity is linked to obesity in animal models." (PMID 33621874, 2021). "Increased activity of SCD-1 has been associated with obesity and insulin resistance." (PMID 32986697, 2020). "Increased expression and activity of SCD-1 has been linked to insulin resistance and obesity." (PMID 32630591, 2020). "Mechanistic studies are needed to investigate whether proteins such as SFRP2, HILPDA, and SCD mediate associations between obesity and its comorbidities." (PMID 30884788, 2019). "However, little is known about the changes in the methylation of the SCD gene promoter with bariatric surgery and its association with obesity and/or insulin resistance levels." (PMID 28393901, 2017). "In SCD null mice, it was observed that diet-induced or leptin deficiency-induced obesity was prevented due to reduced body adiposity and improved insulin sensitivity, suggesting SCD as a potential therapeutic target for metabolic complications associated with obesity." (PMID 28621759, 2017). "Yet, reduced SCD-1 activity has also been associated with adverse vascular outcomes: Inhibition of SCD-1 in hyperlipidemic mice markedly increased aortic atherosclerosis despite protective effects on obesity and IR." (PMID 27768686, 2016). "It has been shown that loss of SCD-1 both prevents obesity and reduces inflammation in adipocytes." (PMID 23298201, 2013). "Ntambi's group demonstrated that loss of SCD-1 function protects mice from developing obesity." (PMID 19761624, 2009). "Moreover, stearoyl-CoA desaturase inhibition is considered an attractive intervention in some obesity-associated pathologies, and the importance of stearoyl-CoA desaturase in the cardiovascular system might be a limitation for developing such therapy." (PMID 36982607, 2023). "SCD is considered a key regulator of energy metabolism with a role in human obesity and dyslipidemia and SCD activity in cumulus cells effectively protects the oocyte against lipid-induced damage by conversion of saturated into monounsaturated fatty acids." (PMID 40676537, 2025). "Obesity-induced insulin resistance significantly suppresses the activity of stearoyl-CoA desaturase (SCD1), thereby reducing the efficiency of converting stearic acid (SA) into OA." (PMID 41233879, 2025). "Growing evidence indicates that fatty acid profiles and the activity of desaturating enzymes—stearoyl-CoA desaturase-1 (SCD1), delta-5 desaturase (D5D), and delta-6 desaturase (D6D)—are important factors in the pathophysiology of obesity." (PMID 41002979, 2025). "Our previous studies utilizing various models have shown the role of SCD under multiple metabolic conditions, including obesity, steatosis, and hyperglycemia." (PMID 40350036, 2025). "SCD, a key enzyme in fatty acid metabolism, has been demonstrated to prevent obesity and diabetes in HFD-fed mice, improving their lipid metabolic status and insulin sensitivity." (PMID 40458826, 2025). "SCD is considered a potential therapeutic target in obesity-related disorders, and its inhibition contributes to the resistance of diet-induced obesity." (PMID 38812531, 2024).
Obesity (continued). "Mice with targeted deletion of the SCD gene exhibited reduced body fat rate, increased insulin sensitivity, and resistance to obesity induced by a high-fat or high-carbohydrate diet." (PMID 38254437, 2024). "Several metabolic and lipidomic pathways are perturbed in the liver and white adipose tissue (WAT) of Mul1(−/−) animals on HFD, including the one driven by Stearoyl-CoA Desaturase 1 (SCD1), a pivotal regulator of lipid metabolism and obesity." (PMID 38725872, 2024). "Like other SCD-deficient mouse models, HFD-fed SCD4−/− mice had lower basal body weight, lower weight gain, lower fat accumulation, and lower obesity." (PMID 39094772, 2024). "A study in high-fat diet-fed rats showed that obesity-prone rats had a higher proportion of the SCD-1 product palmitoleic acid." (PMID 36765351, 2023). "In total, we identified a total of 3,298 differentially expressed genes, among which we discovered key genes such as UBD, RGS2, FASN, and SCD that have functions related to adipogenesis, body weight, obesity, and lipid metabolism." (PMID 38264212, 2023). "We believe these findings have important clinical implications for AD, since SCD inhibitors are currently in clinical trials for obesity and Parkinson’s disease." (PMID 35443751, 2022). "Encouragingly, inhibitors of human SCD have already been approved for clinical trials in obesity (study identifier; NCT02647970) and more recently in Parkinson’s disease (Yumanity); our data support their testing in AD patients as well." (PMID 35443751, 2022). "The decreased palmitoleate to palmitate (16:1/16:0) and stearate to oleate (18:1/18:0) ratios, along with reduced mRNA expression of stearoyl-CoA desaturase (Scd1) in the liver, indicated improvement in obesity." (PMID 36517893, 2022). "Another target protein, stearoyl-CoA desaturase (SCD) is an important regulator of fat metabolism and is implicated in obesity." (PMID 36264868, 2022). "SCD-1 is highly expressed in the hearts of patients with obesity or diabetes, and an increase in SCD-1 alleviates SFA-induced adverse FA catabolism and eventually prevents SFA-induced apoptosis." (PMID 35323653, 2022). "SCD-1 is important in metabolism and metabolic diseases, including obesity and NAFLD, where its activity has been found to increase." (PMID 34441028, 2021). "This can be related to an altered activity of Stearoyl Coenzyme A desaturase-1 (SCD-1), the enzyme that converts saturated FAs 18:0 to monounsaturated FAs 18:1, in obesity." (PMID 33669967, 2021). "Several lines of evidence suggest a pathological role of SCD, notably in obesity, diabetes, and metabolic diseases." (PMID 34576047, 2021). "The major parameters (SREBP‐1c, FAS, and SCD‐1 in the liver) related to obesity showed a decrease in the MF group." (PMID 32405382, 2020). "SCD‐1 induces obesity by catalyzing the desaturation of SFA palmitate and stearate to MUFA palmitoleate and oleate (Li, Berk, McIntyre, & Feldstein, 2009), and FAS and CD36 also play a regulatory role in lipid metabolism (Jung, Cho, Ahn, Jeon, & Ha, 2013)." (PMID 32405382, 2020). "High SCD activity promotes obesity in animals, and plasma activity indices positively associates with fat mass in humans." (PMID 32778150, 2020). "The major transcriptional genes PPAR‐γ, C/EBP‐α, aP2, FAS, and SCD‐1 play an important role in obesity (Wong, Kaneda, & Morita, 2014)." (PMID 32405382, 2020). "Particularly, SCD-1, as the main isoform expressed in the liver, has been proposed as a therapeutic target for obesity." (PMID 31514294, 2019). "Heightened activity of SCD, which catalyzes the synthesis of monounsaturated fatty acids, has been postulated to be a major checkpoint in the pathogenesis of obesity-driven diseases, in particular type 2 diabetes, cardiovascular diseases, and cancer." (PMID 30884788, 2019).
Obesity (continued). "First, high Cys levels have been associated with decreased energy expenditure via increased Scd-1 (stearoyl-CoA desaturase-1) expression and concomitant higher SCD-1 activity, a key lipid synthesizing enzyme and checkpoint in obesity development." (PMID 31321096, 2019). "Other reports have indicated that SCD-1 KO mice are resistant to obesity and exhibit little fatty tissue accumulation." (PMID 29463801, 2018). "Obesity and its metabolic complications are associated with upregulated expression/activity of stearoyl-CoA desaturase-1 (SCD1), a fatty acid desaturase in the endoplasmic reticulum." (PMID 29552293, 2018). "Stearoyl CoA Desaturase-1 (SCD) is considered as playing an important role in the explanation of obesity." (PMID 28393901, 2017). "In agreement with previous studies, we found dissimilar association with obesity for SCD-16 and SCD-18, which are both expressions of SCD-1 activity." (PMID 28465289, 2017). "It was also shown that inhibition of SCD1 protects against diet induced obesity, hepatic steatosis and IR and that higher SCD-activity is associated with higher plasma TAG, similar to what we observed in our experiments." (PMID 28542499, 2017). "Reduced SCD-1 activity in knockout mice has beneficial metabolic consequences, including reduced obesity and improved IR." (PMID 27768686, 2016). "Sleep deprivation has been associated with obesity among adults, and accumulating data suggests that stearoyl-CoA desaturase 1 (SCD1) expression has a relevant impact on fatty acid (FA) composition of lipid pools and obesity." (PMID 27562731, 2016). "Over the last decade there has been much interest in estimating the SCD activity as a putative biomarker for body fat regulation and development of obesity." (PMID 27562731, 2016). "In humans, higher activity of SCD-1 and lower activity of elongase, as described herein for the HCD group, are associated with obesity, hypertriglyceridemia, metabolic syndrome, insulin resistance, and NASH." (PMID 27801862, 2016). "In contrast, mice with skin-specific deletions of SCD-1 showed significantly increased energy expenditures and were protected from high-fat diet-induced obesity." (PMID 26046927, 2015). "This was in contrast to the observation that Elovl6 and SCD ratios increased in tandem in both the ob/ob and dietary models of obesity." (PMID 26679101, 2015). "Concerning fatty acid desaturases, the delta 9 desaturase activity (SCD-1) is increased in obese compared to overweight subjects, confirming data from literature: a high SCD-1 activity has been associated with obesity, and hypertriacylglycerolaemia." (PMID 26511930, 2015). "Aside from obesity, SCD activity has also been shown to be stimulated in conditions with atypical energetic requirements, such as anorexia and intense physical training." (PMID 26147510, 2015). "SCD-1 is also a major player regulating the fatty acid composition of tissues, and SCD -/- mice are resistant to diet induced obesity." (PMID 25198467, 2014). "We further validated the expression of stearoyl-CoA desaturase-1 (SCD1) because it is a critical control point in the development of obesity and insulin resistance." (PMID 23342276, 2012). "Increased SCD activity and/or expression have been reported in hypertriglyceridemia, obesity, nonalcoholic fatty liver disease (NAFLD), and the metabolic syndrome." (PMID 23144998, 2012). "Because of these discoveries, SCD has recently emerged as a possible target for the treatment of diabetes, hyperlipidemia and obesity." (PMID 22046234, 2011). "In accordance with our results, mice lacking SCD-1 are lean with significantly reduced triglyceride storage in the liver and obesity is related to an increased expression of scd-1." (PMID 21949682, 2011).